CCL2 (C-C motif chemokine ligand 2)
Diseases named in the same sentence as CCL2 in open-access papers (continued):
Sharing a sentence is not in itself a finding about the gene and the disease.
infection (continued). "Altered monocyte/macrophage trafficking and CCL2 signals could be particularly important in mediating infant susceptibility to other infections, such as those with Listeria monocytogenes, which require both CCL2 and recruited monocyte-derived cells for clearance." (PMID 26107875, 2015). "Increased levels of CCL2, a chemoattractant for macrophages, may result in increased recruitment of monocytes from bone marrow thus increasing the pool of cells susceptible to infection." (PMID 24083897, 2013). "We show that infection induces robust monocyte chemotactic protein-1 (also known as CCL2) secretion from BMECs, and that CCL2 itself serves as a previously unrecognized driver of BBB dysfunction." (PMID 41646325, 2026). "In our acute infection model, there was a 110-fold elevated Ccl2 mRNA expression, highlighting its role in recruiting immune cells." (PMID 41503211, 2026). "These lipid-laden macrophages secrete an anti-inflammatory cytokine profile (IL-10, TGF-β, CCL2) that establishes a chemotactic gradient, recruiting diverse immune cells and fibroblasts to infection sites." (PMID 40365535, 2025). "Macrophages are essential sources of CCL2, regulating the migration of monocytes and NK cells to the site of infection." (PMID 41156657, 2025). "In summary, TNF, IL-8, and IL-10 specifically increased following infection, whereas CCL2 and IL-18 showed an infection-dependent reduction." (PMID 40794782, 2025). "Cytokine profiling revealed elevated levels of TNF, IL-8, IL-10, and reduced levels of IL-18 and CCL2 in culture supernatants over the time of infection." (PMID 40794782, 2025). "MCP-1 (CCL2), produced by T cells and macrophages, recruits monocytes and Th cells to sites of infection and promotes granuloma integrity." (PMID 41488476, 2025). "The capacity of early and mature retinal organoids to respond to T. gondii tachyzoite infection was determined by RT-qPCR for human cytokine transcripts CCL2, CXCL8, CXCL10, and interleukin-6 (IL6)." (PMID 40137771, 2025). "Early recruitment of inflammatory monocytes depends on CCL2 (MCP-1, also known as Monocyte Chemoattractant Protein-1), produced at the infection site upon activation by platelet-derived growth factor." (PMID 41463020, 2025). "The infection induced G-CSF and CCL2 on 3 dpi, while CCL5 increased compared with mock infected by 7 dpi." (PMID 40854598, 2025). "Our results indicated that both IL-8 and CCL2 mRNA were significantly upregulated at 12 h post infection (pi)." (PMID 40353220, 2025). "CCL2 involved in the recruitment of monocytes and macrophages to sites of infection and plays a vital role in immune response to viral challenges." (PMID 40552037, 2025). "Monocyte-derived macrophages migrate to the site of infection in response to the activation on chemoattractants, such as CCL2/MCP-1, induced by CHIKV." (PMID 41156657, 2025). "Monocyte Chemoattractant Protein-1 (MCP-1), also known as CCL2, plays a crucial role in orchestrating the inflammatory cellular infiltration by recruiting monocytes to sites of infection or injury." (PMID 41176818, 2025). "We found that maSARS-CoV-2–infected mice had increased production of G-CSF, IL-12 p40, CCL2, and CCL5, which are often linked to monocyte recruitment, a prominent feature of this infection." (PMID 40854598, 2025). "Specifically, estradiol alleviates virus-induced immunopathology by downregulating the expression of pro-inflammatory cytokines such as TNF-α, IL-6, and CCL2, thereby mitigating excessive pulmonary inflammation and improving infection outcomes." (PMID 40872527, 2025). "Classical monocytes are recruited to infection and inflammation sites via the CCL2/CCR2 pathway, releasing cytokines like TNF-α and iNOS to kill pathogens and enhance adaptive immunity." (PMID 40370772, 2025).
infection (continued). "Whilst concentrations of MMP-9 and CCL2 were reduced upon infection, IFN-β and CXCL10 were induced as the infection course progressed, with significant increases over mock after 48 hpi and 72 hpi for both the USUV- and WNV-infected conditions." (PMID 40295794, 2024). "Infection with CHIKV also increased the levels of inflammatory cytokines and chemokines (TNF-α, IL-6, IL-10, and CCL-2), which are associated with severity, morbidity, and mortality in patients." (PMID 39339151, 2024). "In the periphery in mice, CCL2 is produced during recognition of the T. gondii protein profilin, which leads to the recruitment of Ly6Chi monocytes to sites of infection." (PMID 38206985, 2024). "We found that microglia and brain-infiltrating myeloid cells produce high levels of CCL2 during acute infection in close proximity to the parasites." (PMID 38206985, 2024). "CCL2, as a small chemokine, attracts monocytes, T-memory cells, and dendritic cells (DCs) to sites of infection and inflammation." (PMID 38931342, 2024). "The observed low levels of CCL2 imply that infections with the cdh1Δ mutant and CDH1OE strains exert a limited effect on macrophage activation, resulting in fewer monocytes/macrophages migrating to the lungs." (PMID 39728387, 2024). "Human infection with MPXV is associated with increased levels of ILs, C-C motif chemokine ligand 2 (CCL2) and CCL5, and a significant decrease in tumor necrosis factor alpha (TNF-α), IFN-γ, and IL-2 and IL-12." (PMID 38510963, 2024). "We measured ccl2 expression in the brain using real-time qPCR and detected a 70% decrease in ccl2 mRNA levels in the brains of the knockout mice during infection." (PMID 38206985, 2024). "The development of demyelination following TMEV infection correlates with an increase in the CCL2 expression." (PMID 38257819, 2024). "By 24 hours after infection, we also detected increased expression of genes involved in a broader inflammatory response, including Ccl2, Cxcl9, Cxcl10, and Ccl7, which were upregulated across the major LNSC subsets." (PMID 38194268, 2024). "At 24h, all the assayed cytokines/chemokines apart from MCP-1 (CCL2) were significantly induced by infection." (PMID 38704381, 2024). "Increased levels of chemokines like CXCL8 and CCL2 promote the recruitment of immune cells to the site of infection, aiding in parasite clearance." (PMID 38694310, 2024). "Among those GO terms, at the acute infection stage, some targeted DEmRNAs (e.g., Ccl2, Lgals3, H2-DMb2, Ripk2, and Ndfip1) were enriched in the “regulation of T cell activation” term (GO:0050863)." (PMID 38229193, 2024). "To investigate the cells that produce CCL2 during acute infection, we used CCL2-RFP reporter mice, in which all cells expressing CCL2 also express RFP." (PMID 38206985, 2024). "We have observed that a reduction in miR-126 transcript alters normal macrophage phenotype and function through its involvement in the Cxcl12/Ccl2/Ccr2 axis and coupled with concurrent mTOR inhibition, increases cell death at the site of infection." (PMID 38307625, 2024). "We observed a similar pattern, as Pam3CSK4 induced Ccl2 expression in uninfected animals, but decreased Ccl2 levels in the context of 5 PFU infection." (PMID 38935789, 2024). "Infection of both cell lines with F. nucleatum resulted in induction of the chemokine MCP-1/CCL2 which has been shown to induce VEGF-A in OSCC." (PMID 39286811, 2024). "Collectively, activation of the TLRs and the subsequent expression of CCL2 following infections can play a crucial role in mediating the inflammatory response in OA, leading to synovitis, cartilage destruction, and disease progression." (PMID 39076996, 2024). "PARP-1 promoted the migration of natural killer (NK) cells to the site of infection, via NF-κB-mediated production of CCL2 by macrophages." (PMID 39201718, 2024).
infection (continued). "In vivo experiments in mice of catheter-induced S. aureus infection showed a significant reduction in cytokine secretion of IL-1β, TNF-α, CXCL2, and CCL2 during biofilm infection." (PMID 38571946, 2024). "Nevertheless, it will prerogative in any clinical study to survey infection rates following CCL2 antibody therapy." (PMID 38961074, 2024). "During tissue injury or infection, CCL2 expression is upregulated to recruit monocytes and other immune cells to sites of inflammation." (PMID 39334887, 2024). "In a longer duration of SARS-CoV-2 infection, from 14 days to four weeks, CCL-2 levels were reported to be similar between severe and mild infection." (PMID 38646483, 2024). "In the TMEV model, hippocampal neurons are the predominant source of CCL2 upon infection, and neuron-specific genetic ablation leads to reduced infiltration of monocytes within the brain." (PMID 38997413, 2024). "We determined that the cells producing the potent chemokine, CCL2, changed over the course of infection: myeloid cells were the main CCL2 producers during acute infection, whereas astrocytes became the dominant CCL2 producers during chronic infection." (PMID 38206985, 2024). "On average, 10.33% of microglia, 7.77% of Ly6Chi and 12.71% of Ly6Clo monocytes, and 1.14% of neutrophils were also positive for CCL2-RFP during infection." (PMID 38206985, 2024). "Following infections and activation by PAMPs, TLRs trigger signaling pathways that produce inflammatory mediators, including CCL2." (PMID 39076996, 2024). "Chemotactic cytokines (chemokines), including CXCL8 and CCL2, attract immune cells, such as neutrophils and monocytes, to the site of infection." (PMID 38694310, 2024). "CCL2 is transcribed in the brain as early as 7 days post-infection (DPI) and persists at 10, 30, and 60 DPI." (PMID 38206985, 2024). "CCL2 is an important regulator of myeloid cell and T cell recruitment during inflammation and infection." (PMID 38973385, 2024). "The gene expression levels of the pro-inflammatory cytokines, including IL-6, TNF-α, and CCL2, were significantly elevated in the infection group compared to the control group (P < 0.01 and P < 0.05, respectively; n = 5; Tukey test)." (PMID 38233485, 2024). "Lung tissue from the mice revealed four of these, IL1-RA, IL-6, CCL2, and IL-12p40, to be upregulated with low-inoculum infection by QPCR." (PMID 39474424, 2024). "The analysis based on publication years shows that studies from 2010 to 2019 report higher MCP-1/CCL-2 levels in severe infections." (PMID 39567619, 2024). "This mechanim of host defense cooperates with TLR-dependent and independent production of CCL2 that leads to the recruitment of monocytes to the site of infection that are indispensible for host resistance to T. gondii." (PMID 38377133, 2024). "At the same time, the massive secretion of CCL2 after infection leads to an excessive inflammatory response in the organism." (PMID 38803488, 2024). "During infection, CCL2 recruits CCR2+ monocytes out of the bone marrow into the circulation, and ultimately into injured or inflamed tissues." (PMID 38206985, 2024). "In cases of infection-related PTB an increase in CCL2 expression was observed in uterine smooth muscles cells, in the placenta and amniotic fluid." (PMID 37770883, 2023). "Infection by Alpha resulted in significant increase of several inflammatory cytokines such as CCL2, CXCL10 and IL-6 over a longer period of time compared to Ancestral strain." (PMID 37507719, 2023). "The results presented here place the role of CCL2 in NCI as the signal to HIV-infected monocytes to enter the brain where infection and disease ensue." (PMID 37085605, 2023). "Monocytes are recruited to the site of infection during the early phase by IL-6, IL-8, CCL2, CCL5, and MIP-1α derived from infected AECs and macrophages." (PMID 37896776, 2023).
infection (continued). "Our data suggest Theracurmin has an immunomodulatory (CCL2, IL-15, CK and tissue leukocyte infiltration) and a trypanocidal effect (on circulating parasites) during experimental infection triggered by the Colombian strain of T." (PMID 37505639, 2023). "CCL2 is produced by both the epithelium and inflammatory cells and serves as a monocyte chemoattractant to sites of infection and wound healing." (PMID 36982810, 2023). "In AGM, the expression of Ccl2, Ccl3, Ccl4, Ccl7, and Ccl8 together with Cxcl10 and Cxcl11 also increases during infection, although more rapidly and with a more marked expression in nonpolarized rAM than in hamsters." (PMID 37350967, 2023). "Chemokine expression remained largely unaffected in lymph nodes, with only a slight increase in Ccl2 expression at 7 weeks post-infection." (PMID 36675185, 2023). "Another study using VARV-infected cynomolgus macaques reported cytokines such as IFN, IL-6, CCL4 (also recognized as MIP1), CCL2 (also identified as MCP1), and IL-8 were all elevated in the first 4 days after infection." (PMID 37533932, 2023). "CCL2 recruits cells of the immune system (monocytes, lymphocytes etc.)to the sites of inflammation produced by tissue injury or infection." (PMID 37430267, 2023). "We evaluated the systemic and tissue parasitism, the survival and the body mass rate, the release of inflammatory mediators (TNF, IL-6, IL-15, CCL2 and creatine kinase) and the tissue inflammation at day 30 post-infection." (PMID 37505639, 2023). "We addressed this question during infection of conventional and CCL2 knockout mice with EcoHIV in which NCI can be verified in behavioral tests." (PMID 37085605, 2023). "It has been shown that CCL2 in association with IFN-γ is a relevant biomarker of subclinical infection of HHC, as also a parameter for early infection monitoring." (PMID 37187734, 2023). "Infection of MDMs with tubercle bacilli led to an increase in the concentration of most tested cytokines except CCL2 and IL-27." (PMID 37781389, 2023). "CCL2 is a major player in the recruitment of immune cells at site of infections, while TNF-α, IL-6 and IL-1β are proinflammatory cytokines." (PMID 37624851, 2023). "Demyelinating patterns in NCS can be suggestive of acute neuritis as well as the beginning of the infection.MCP-1/CCL2 was found in high levels in patients with PNL and was also significantly associated with demyelinating patterns in NCS." (PMID 38116016, 2023). "CCL2 is produced and released by various cells, such as endothelial cells, fibroblasts, and macrophages, and attracts monocytes to the site of pathogen infection." (PMID 36839438, 2023). "We observed a significant up-regulation of the chemokine CCL2 in the late infection states of lungs in 6 individual studies (GSE155241, GSE148697, GSE160435, GSE157057, GSE147507, and GSE184536)." (PMID 37497545, 2023). "Other serum cytokines measured were either unchanged during infection (CCL2) or below the limit of detection (IL-4, IL-1β and IL-10)." (PMID 37837930, 2023). "Compared to B lineage isolates, infection of mice with UT21 had lower levels of CCL2, CCL3, CCL4, TNF-α, and IL-1β." (PMID 36992320, 2023). "We used adherent HeLa-CCL2 epithelial cells as an infection model in a 96-well format and infected them with S. aureus at a standardised multiplicity of infection (MOI)." (PMID 37289634, 2023). "Ccr5, Ccl2, Ccl5, and Ccl7 were among the most significantly upregulated chemokine genes in SC samples at 1 wk post-infection." (PMID 36490282, 2022). "CCL2 expression increases significantly during the early acute phase of infection and then gradually diminishes as the disease progresses." (PMID 35958594, 2022). "Regarding inflammatory response, ChP organoids showed an increase in inflammatory cytokines CCL7, interleukin-32 (IL-32), CCL2, MCP1, IL-18, and IL-8 upon infection." (PMID 35337041, 2022).
infection (continued). "In serum, there was a lower induction of CCL2 and CXCL10 during the early stages of infection in beta variant-infected mice." (PMID 36005818, 2022). "Infection led to robust induction of chemokine and interleukin genes, including Il1b, Il6, Ccl2, Ccl3, Ccl4, Ccl7, Cxcl1, Cxcl2, Cxcl5, Cxcl9, and Cxcl10, and related receptor genes, including Ccr1, Ccr4, Ccr5, Ccr5, Ccr7, Cxcr2, Cxcr5, Il1r2, and Il1rn." (PMID 35487885, 2022). "The other chemokines detected in this study involved in monocyte, T and NK cell recruitment were CCL2, CCL4 and CCL23, which were upregulated in the medium and high dose groups, resulting in an increased number of cells susceptible to infection." (PMID 35854219, 2022). "Several studies have proposed C-reactive protein (CRP), procalcitonin, or the chemokine (C-C motif) ligand 2 (CCL2) as markers of infection." (PMID 36292107, 2022). "CCL2 attracts monocytes, memory T-cells, and dendritic cells to sites of infection or inflammatory areas triggered by tissue damage." (PMID 36482905, 2022). "Type I IFN receptor mediates the expression of CCL2 induced by modified vaccinia virus Ankara, which in turn recruits NK cells and T lymphocytes to the site of infection." (PMID 35281057, 2022). "Microglia suffice to uptake myelin in response to MHV–JHM infection as demyelination was evident in CCL2−/− mice, which exhibit significantly impaired CNS recruitment of BMDM." (PMID 36333761, 2022). "Brain lesions caused by trauma, infection, or neurodegenerative disease result in the localised production of chemoattractants CCL21 and CX3CL1 by neurons and astrocytes, and MCP-1/CCL2 and SDF-1α/CXCL12 by activated microglia adjacent to the lesion." (PMID 36359810, 2022). "CCL2 has been described as one of the innate immunity genes immediately activated in the context of infection in vitro." (PMID 35492305, 2022). "The transcriptional level of macrophage chemokine CCL2 (MCP‐1) was also significantly upregulated on the 4th day (p = 0.0328), 5th day (p = 0.0004), 6th day (p = 0.0002), and 7th day (p = 0.0002) after infection." (PMID 34766463, 2022). "Produced by microglia, neurons, astrocytes and mononuclear phagocytes, CCL2 recruits monocytes to the site of infection during inflammatory events." (PMID 36590292, 2022). "Previous studies have reported a detrimental effect of type I IFN during Mtb infection due to increased production of CCL2, which is mainly responsible for neutrophil infiltration to the infection site." (PMID 35672321, 2022). "We did, however detect significant reductions of plasma CCL2 concentrations by 12.8% and 13.6% at days two and four after infection, respectively, relative to uninfected controls." (PMID 36365071, 2022). "We next quantified the gene expression of IL-6 and CCL-2 in the lungs of K18-hACE2 mice at day 3 after infection." (PMID 35746611, 2022). "Infection with A7UF induced an increased expression of Ccl2, Icam1, Tgfb1, Eng, and matrix metalloproteinase (Mmp) 2 and 9 with no change in the expression of the tissue inhibitor of metalloproteinase (Timp)." (PMID 36483452, 2022). "During C. neoformansinfection, the production of the chemokine MCP-I (also known as CCL2) by alveolarmacrophages exerts a key role in chemotaxis, stimulating the migration ofmononuclear cells from the bloodstream to the infection site." (PMID 35910486, 2022). "CCL2 is produced in the central nervous system (CNS) due to an immunological response to infection, damage, or inflammatory reaction in the CNS." (PMID 35677043, 2022). "CCL2, known as MCP-1 (monocyte Chemoattractant Protein 1), attracts T cells, dendritic cells and monocytes in patients with active infection, and bridges innate and adaptive immunity." (PMID 35163330, 2022). "Both types of fibroblasts secrete CCL2 in response to pathogens so as to alert immune cells and recruit them to the sites of infection." (PMID 35546662, 2022).